CDC42SE1 (CDC42 small effector 1)
Description:
Probably involved in the organization of the actin cytoskeleton by acting downstream of CDC42, inducing actin filament assembly. Alters CDC42-induced cell shape changes. In activated T-cells, may play a role in CDC42-mediated F-actin accumulation at the immunological synapse. May play a role in early contractile events in phagocytosis in macrophages.
Synonyms: SPEC1; SCIP1
Tractability: Antibody: its Gene Ontology location is reachable by antibodies, with high confidence; UniProt places it where antibodies can reach, with medium confidence. PROTAC: ubiquitination databases record sites on it.
Gene: Protein-coding gene on chromosome 1 (151,050,971 to 151,070,325, reverse strand). Ensembl gene ENSG00000197622.
Subcellular location: Cytoplasm, cytoskeleton; Cell membrane
Subcellular location (Human Protein Atlas): Cell Junctions
Gene Ontology:
Molecular function: protein binding; GTPase inhibitor activity; small GTPase binding
Biological process: signal transduction; regulation of Rho protein signal transduction
Cellular component: cell junction; plasma membrane; cytoskeleton
Genetic constraint (gnomAD): Loss-of-function variants: 6 observed, 6.26 expected, observed/expected ratio (o/e) 0.96, 90% interval 0.52 to 1.74. That is too few expected variants to judge how well the gene tolerates losing a copy. Missense variants: 56 observed, 84.26 expected, observed/expected ratio (o/e) 0.66, 90% interval 0.54 to 0.83. Synonymous variants: 19 observed, 28.04 expected, observed/expected ratio (o/e) 0.68, 90% interval 0.47 to 0.99.
Homologues: Orthologues: chimpanzee CDC42SE1 (100% identical), macaque CDC42SE1 (100% identical), pig CDC42SE1 (100% identical), rabbit CDC42SE1 (100% identical), mouse Cdc42se1 (99% identical), guinea pig CDC42SE1 (97% identical), rat Cdc42se1 (97% identical), tropical clawed frog cdc42se1 (67% identical), zebrafish cdc42se1 (62% identical). Paralogues in human: CDC42SE2 (49% identical).
Diseases named in the same sentence as CDC42SE1 in open-access papers:
CDC42SE1 is named in the same sentence as 8 diseases in open-access papers, as found by Europe PMC text mining. Sharing a sentence is not in itself a finding about the gene and the disease. The quoted sentences say what the papers report.
skin cancer (2 papers, 2019 to 2022). "In order to characterize the role of CDC42SE1 in skin cancer, we analyzed the expression of CDC42SE1 in the SCC samples and matched perilesional controls (n = 5) using qPCR." (PMID 30717410, 2019). "We found that the expression of CDC42SE1 was reduced in human skin cancer samples relative to matched perilesional control." (PMID 30717410, 2019). "In order to characterize the role of CDC42SE1 in skin cancer and to identify the signaling pathways regulated by CDC42SE1, we focus our effort on the A431 cell line." (PMID 30717410, 2019). "Our results suggest that CDC42SE1 is downregulated in skin cancer to promote tumorigenesis, and thus CDC42SE1 might be an important marker of skin cancer progression." (PMID 30717410, 2019). "In summary, we found that the expression of CDC42SE1 was reduced in human skin cancer samples compared to controls; similarly, we also found that the expression of CDC42SE1 was reduced in skin cancer cell lines, and A431 cells compared to normal keratinocytes HaCaT cells." (PMID 30717410, 2019). "Thus, our study has shown that downregulation of CDC42SE1 expression in cancer promotes tumorigenesis, and may be a novel marker for skin cancer development and progression." (PMID 30717410, 2019). "Thus, reduced expression of CDC42SE1 in skin cancer of patient samples may promote cell proliferation and tumorigenesis." (PMID 30717410, 2019). "However, the role of CDC42SE1 in cell proliferation of skin cancer remains unknown." (PMID 30717410, 2019). "However, the role of CDC42SE1 in skin cancer has not been characterized." (PMID 30717410, 2019).
Epidermoid carcinoma (1 paper, 2019). "To identify an in vitro model, we checked for the expression of CDC42SE1 in human immortalized keratinocytes (HaCaT), HSC5 (human skin squamous cell carcinoma cell line), and A431 (Epidermoid carcinoma cell line) cell lines." (PMID 30717410, 2019).
mastitis (1 paper, 2023). Inflammation of breast tissue during lactation or postpartum due to an obstructed duct or infection. "Furthermore, the precise role of CDC42SE1 hub-hub lncRNA in mastitis inflammation and immunity is still unclear." (PMID 37620551, 2023).
cancer (1 paper, 2019). A tumor composed of atypical neoplastic, often pleomorphic cells that invade other tissues. "Taken together, in vitro and in vivo findings demonstrate that CDC42SE1 regulates the cancer cell proliferation and tumor formation." (PMID 30717410, 2019). "Furthermore, we found that CDC42SE1 is highly expressed in normal keratinocytes (HaCaT), whereas its expression is reduced in carcinoma cell lines (A431 and HSC-5)." (PMID 30717410, 2019). "Thus, the results indicate that CDC42SE1 is highly expressed in normal keratinocytes while being reduced in carcinoma cell lines." (PMID 30717410, 2019). "CDC42SE1 is a small effector of CDC42 and their function in cancer remains unknown." (PMID 30717410, 2019). "The role of CDC42SE1 in cancer has not been characterized to date." (PMID 30717410, 2019).
infection (1 paper, 2015). The state of being infected such as from the introduction of a foreign agent such as serum, vaccine, antigenic substance or organism. "GSEA at 24 h indicated that genes involved in infection, TLR, chemokine and cytokine signaling are enriched as before, but genes involved in phagocytosis are also enriched, including Vav1, Sirpa, Cdc42se1, Cdc42ep2, Fcgr2b/3, and Coro1a." (PMID 25888408, 2015).
tumor (1 paper, 2019). "Overexpression of CDC42SE1 in A431 cells caused significant reduction in cell proliferation, colony size in soft agar, and tumor size in xenograft nude mice compared to A431Ctrl cells." (PMID 30717410, 2019). "Thus, the results suggest that CDC42SE1 overexpression in A341 cells inhibit xenograft tumor growth." (PMID 30717410, 2019). "In addition, overexpression of CDC42SE1 reduced colony numbers and size of A431SE1 cells compared to A431SE1-H38A and A431Ctrl cells in clonogenic assay, suggesting that CDC42SE1 inhibits tumor initiation and cell survival in A431 cells compared to A431Ctrl and A431SE1-H38A cells." (PMID 30717410, 2019).
CDC42SE1 also shares sentences with these, for which no sentence is quoted: head-neck squamous cell carcinoma (1 paper); skin squamous cell carcinoma (1).